DCC (DCC netrin 1 receptor)
Diseases named in the same sentence as DCC in open-access papers (continued):
Sharing a sentence is not in itself a finding about the gene and the disease.
tumor (continued). "This antibody could block Netrin-1/Unc5B interaction to inhibit Netrin-1 induced tumor cell growth but does not inhibit Netrin-1/DCC interaction, suggesting that DCC and Unc5B also could interact with different Netrin-1 motifs in the EGF2 domain." (PMID 28245592, 2017). "The possible presence of LOH in CDKN2A and DCC may increase the likelihood of tumours being non-informative for these two markers." (PMID 18594522, 2008). "For DCC mRNA, transcripts could be detected in all analysed normal tissues (eight out of eight) by RT-PCR, whereas 6 of the 15 tumours were negative." (PMID 9484816, 1998). "In tumour tissues, no DCC protein was seen in 11 out of 16 samples (69%)." (PMID 9484816, 1998). "Interestingly, the loss of protein frazzled (a homolog of DCC) inhibits MET suggesting that DCC may normally drive the non-migratory state of cells by promoting MET, while its progressive decline with tumor growth eventually leads to an apparent EMT and metastatic migration." (PMID 32117748, 2020). "IHC staining confirmed the downregulation of FBXW7 in cancer tissues compared with tumor adjacent nontumorous tissues in IHCC and PHCC, but not in DCC." (PMID 25749036, 2015). "r = -.15) and a weakly significant negative correlation between tumor grade and ER (ICC, r = -.17) as well as PR (ICC, r = -.24; DCC, r = -.14)." (PMID 22642691, 2012). "Although patients without neoplasia were selected, aberrant methylation of the CCNA1, DAPK, DCC and MGMT genes was present in the pretreatment oral rinse samples in all participants of both groups, an epigenetic event that is the target of action of valproic acid." (PMID 34385507, 2021). "Because both DCC and UNC5C share the same netrin ligand and are colocalized in the gut, we hypothesized that solitary inactivation of either DCC or UNC5C may not be sufficient to promote tumor development in the stomach." (PMID 26207151, 2015).
cancer (128 papers, 1993 to 2026). A tumor composed of atypical neoplastic, often pleomorphic cells that invade other tissues. "The hot spot mutation R661*/Q of DCC occurred in 8 patients with UCEC out of 15 patients with 6 cancers (OV, SKCM, BRCA, COAD, BLCA, and UCEC)." (PMID 41407823, 2025). "Hyper-methylated genes included previously reported targets of recurrent hyper-methylation in OSCC, such as DDAH2, CCNA1, DCC, as well as some cancer-associated genes including HRAS." (PMID 38589501, 2024). "Loss of DCC expression was detected in several cancers (stomach, prostate, ovary and testes, esophagus, breast, and hematologic malignancies)." (PMID 36136711, 2022). "DCC encodes the receptor deleted in colorectal cancer (DCC), which recruits proteins to promote axon outgrowth and guidance during neurodevelopment, and has been shown to interact with a Ras inhibitor." (PMID 28076348, 2017). "Our meta-analysis results showed that DCC rs714 polymorphism was associated with increased risk of cancer in Asian populations." (PMID 26891331, 2016). "Since SNPs are emerging as promising biomarker of cancer susceptibility, here, we aimed to execute a meta-analysis of DCC (rs714 A > G) and PSCA (rs2294008 C > T, rs2976392 G > A) polymorphism to demonstrate the more accurate strength of these associations." (PMID 26891331, 2016). "In the present meta-analysis, we found that DCC rs714 conferred a significantly increased risk of cancer only in Asians." (PMID 26891331, 2016). "Loss of heterozygosity (LOH), the most common genetic alteration of the DCC gene, is established to be implicated in pathogenesis of various cancers." (PMID 26891331, 2016). "Multiple studies have investigated the association of gene variant of Deleted in colorectal carcinoma (DCC) and Prostate Stem cell antigen (PSCA) with various cancer susceptibility; however, the results are discrepant." (PMID 26891331, 2016). "We found that among the cancers with complete loss of DCC expression, 5/7 cancers (71 %) demonstrated both DCC promoter methylation and 18q LOH." (PMID 26207151, 2015). "The rs714 has been shown to be associated with loss of heterozygosity (LOH) and decreased expression of DCC in various cancers." (PMID 26602921, 2015). "Loss of heterozygosity at 18q, which includes the Deleted in Colorectal Cancer (DCC) gene, has been linked to many human cancers." (PMID 21672235, 2011). "LOH at 18q is associated with decreased DCC expression and has been linked to many other types of cancer, including neuroblastomas, hematologic malignancies, and gastric, endometrial, prostate, ovarian, esophageal, testicular, breast, and glial cancers." (PMID 21672235, 2011). "DCC is the most likely target of LOH because loss or reduction of DCC expression has been found in many types of cancers." (PMID 11461076, 2001). "The main pathways of methylome biomarkers were associated with calcium signalling (CACNA1E, RYR2, RYR3), cancer pathways (DCC, RASSF1, WNT1, CTNNA2), multiple neurodegenerative diseases (WNT1, DNAI1, RYR2, RYR3), immune system disorders and cell adhesion (HLA-DRA, HLA-DRB1, HLA-DRB5)." (PMID 40524349, 2025). "Besides SMAD4 and DCC, this region encloses known cancer-related genes that were significantly associated with a higher relapse probability of early-stage primary tumors, namely SMAD2 and BCL2." (PMID 36085309, 2022). "We note with interest that recent structural studies of deleted in colorectal cancer (DCC), a netrin receptor, important for axon navigation, suggests the associations of DCC with both its extracellular and intracellular binding partners play roles in mediating the receptor clustering." (PMID 31924785, 2020).
cancer (continued). "In previous studies, DCC gene variants were found to be correlated with some types of cancer." (PMID 27127179, 2016). "Further, DCC gene variants have been associated with increased susceptibility of various cancers." (PMID 26891331, 2016). "Some evidence that DCC inactivation may in fact be associated with tumorigenic growth properties in colon and other cancers has been obtained." (PMID 15956977, 2005). "Loss of heterozygosity of chromosome 18q and/or decreased DCC expression have also been seen in various other cancers, including gastric, prostate, endometrial, ovarian, oesophageal, breast, testicular, glial, neuroblastoma and haematologic malignancies (see for review Mehlen and Fearon, 2004)." (PMID 15956977, 2005). "The amino acid sequence of DCC shares homology with neural cell adhesion factor (NCAM) and other related cell surface glycoproteins, which suggests that loss of DCC function may lead to decreased cell-to-cell contact and adhesion, thus enhancing the metastatic ability of cancer cells." (PMID 39532956, 2024). "However, it is unclear if loss of DCC is the specific underlying cause of these cancers." (PMID 21672235, 2011). "Here, we investigated the roles of netrin receptors, uncoordinated-5 homologues (UNC5A, -B, -C, and -D), deleted in colorectal cancer (DCC), and the DCC paralog (neogenin) during myogenic differentiation, focusing on fast-twitch myotube formation." (PMID 41703986, 2026). "The proteins DARPP32 and the Dopa-Decarboxylase AADC/DCC, which are expressed in dopaminergic neurons but also in certain cancer cells displayed high expression levels in two of the GS- and three of the GBM-derived cell lines." (PMID 38306361, 2024). "If it binds to the deleted in colorectal cancer (DCC) or neogenin receptors, it attracts the axon, whereas if it binds to the DCC/uncoordinated A–D receptor complex, the result is the repulsion of axons." (PMID 38136245, 2023). "Netrin 1 (NTN1) and deleted in colorectal carcinoma (DCC) regulate midline zipper glia (MZG) organization during interhemispheric fissure (IHF) remodelling." (PMID 33871356, 2021). "The explanation also accounts for DCC-expressing cells being sensitive to anti-cancer drugs, whereas truly metastatic cells are relatively resistant." (PMID 32117748, 2020). "Deleted in colorectal cancer (DCC) is identified as the receptor that mediates Netrin-1-induced neuronal sprouting." (PMID 31822662, 2019). "The functional enrichment of DEGs in ESCC were mainly correlated with cell cycle, DNA replication, deleted in colorectal cancer (DCC) mediated attractive signaling pathway, and Netrin-1 signaling pathway." (PMID 31139019, 2019). "DCC directs cell invasion through the basement membrane, an essential step in the pathological progression of human cancer." (PMID 27127179, 2016). "Genetic interaction data suggest that draxin acts through Deleted in colorectal cancer (DCC) and Neogenin (Neo1), to regulate thalamocortical projections in vivo." (PMID 26659141, 2015). "In contrast, 8/33 cancers (24 %) showed focal loss of DCC expression and both methylation and LOH, 5/33 cancers (15 %) showed LOH alone, and 12/33 cancers (36 %) displayed methylation alone." (PMID 26207151, 2015).
cancer (continued). "CDON resembles in many aspects DCC (Deleted in Colorectal Cancer), the prototypical netrin-1 dependence receptor." (PMID 23940460, 2013). "The secreted factor netrin-1 is upregulated in a fraction of human cancers as a mechanism to block apoptosis induced by netrin-1 dependence receptors DCC and UNC5H." (PMID 24293316, 2013). "Since this change is next to the cell membrane, it may have repercussions on the functionality of the DCC protein product, perhaps causing inactivation, similar to the inactivation caused by loss of heterozygosity and transcript suppression observed in other cancer types." (PMID 23892400, 2013). "According to the earlier studies-specific chromosomal region, 16q21-24 involved in large region (including 8p, 6q, and 18q distal and proximal to DCC gene) revealed AI in different types of human cancer including prostate." (PMID 23288724, 2013). "Mice mutant for deleted-in-colorectal-carcinoma (DCC), which is a netrin-1 dependence receptor, lack submucosal gut ganglia." (PMID 23671607, 2013). "Our findings on neogenin methylation were in harmony with other dependent receptors such as DCC and UNC5H, where their loss of expression in several cancers was due to promoter methylation." (PMID 22666451, 2012). "The NTN1 and DCC mRNAs were quantified by real-time RT-PCR in normal, benign and cancer ovarian tissues." (PMID 21789787, 2011). "Genome-wide methylation-associated biomarkers were involved in the pathways of neurodegeneration-multiple diseases (13%), cancer-related pathways (DCC, RASSF1, WNT1, CTNNA2; 13%), and Hippo, calcium signalling, cell adhesion and immune system-related pathways (all 10%)." (PMID 40524349, 2025). "In addition, although there were some cases in which saliva samples were hypermethylated despite low DCC methylation in carcinoma tissues and vice versa, DCC methylation in saliva was detectable in almost all cancer cases." (PMID 38538728, 2024). "Intriguingly, it was demonstrated that the nematode homologue of PGRMC1, VEM-1, physically interacts with C. elegans UNC-40, the nematode homologue of the mammalian cell surface receptor ‘deleted in colorectal cancer’ (DCC), which is one of the receptors mediating netrin-1 function." (PMID 39007013, 2024). "High NTN-1 signalling through UNC5B and DCC during tumorigenesis has been related to cancer cell proliferation and migration by up-regulation of the proto-oncogene YAP, a downstream signalling of the Hippo pathway, important in cell proliferation and apoptosis." (PMID 36831381, 2023). "In addition to the likely pathogenic variant on the DCC gene, we also identified a truncating VUS in the ECT2L gene, along with 11 variants classified as VUS in cancer-related genes." (PMID 36077770, 2022). "For example, binding of netrin-1 to deleted in colorectal cancer (DCC), possibly together with Unc5, repels migrating GABAergic neurons from the ventricular zone of the ganglionic eminence, whereas binding to α3β1 integrin promotes cortical interneuron migration." (PMID 33520982, 2020). "Moreover, several enriched guidance molecule pathways (ephrin signaling, semaphorin interactions, integrin, DCC-mediated attractive signaling) are noted as cancer-drug targets." (PMID 29507679, 2018). "Importantly, cancer has been described in all vertebrates including birds and most of the missing genes such as SMAD467, SKA169, MEX3C70 and DCC have been linked to tumorigenesis." (PMID 28240285, 2017). "On the other hand, DCC is suggested to have an anti-metastatic role, meaning that it may only contribute to cancer in the context of a preexisting condition." (PMID 29023534, 2017).
cancer (continued). "As discussed in the previous section, DCC is believed to have an anti-metastatic role, so its reduced functionality might have a synergistic effect with other cancer driving events." (PMID 29023534, 2017). "Furthermore, in line with these observations, DCC and UNC5H are silenced in many cancers, either by loss of heterozygosity or epigenetic mechanisms." (PMID 27378792, 2016). "With chymotrypsin present in chyme, blood and tissues, these proteases may contribute to cancer development by depleting DCC and neogenin." (PMID 27716118, 2016). "Evidence indicated that DCC was frequently down-regulated in many cancers." (PMID 27127179, 2016). "CASP8 and DCC have been associated with increased aggressiveness and poor prognosis in several cancers including NB,25, 26, 27, 28 and in NB lack of CASP8 has been found to promote metastasis." (PMID 25664931, 2015). "DCC, which displays an overall low expression in the screened cancer cell lines, is the netrin-1 receptor showing the largest spectrum of upregulation as DCC expression was strongly increased in 40, 40 and 53% of cell lines in response to, respectively, Cisplatin, 5FU and Taxol." (PMID 24293316, 2013). "In addition, we have shown that these traits confer to the pair SHH/CDON a key regulatory role in cancer progression as recently shown for the dependence receptor DCC." (PMID 23940460, 2013). "Indeed, some families of axon guidance molecules were also reported to participate in cancer invasion: plexins/semaphorins/neuropilins, ephrins/Eph receptors, netrin/DCC/UNC5." (PMID 24212788, 2011). "It is therefore possible that using an experimental design more comparable to the one employed here, one in which clones of mutant DCC cells are generated and rescued from death, could reveal cancer phenotypes in mice." (PMID 21672235, 2011). "As examples, BIG-2 could be considered a neuronal protein but is also an adhesion molecule; deleted in colon cancer (DCC) is a cancer-related protein but also a neuronal protein." (PMID 18088439, 2007). "For example, genes that encode DRs such as DCC, neogenin, UNC5B, UNC5C, or TrkC are repressed in multiple cancer types, while cancer cells can also escape DR‐mediated apoptosis through autocrine overexpression of ligands including DKK1, Netrin‐1, NT‐3, Sema3E, or HGF." (PMID 34542930, 2021). "Considering the panoptic role of DCC (rs714) and PSCA (rs2294008, rs2976392) polymorphism in the carcinogenesis, and increasing number of reports on different cancer in recent years, there is a prerequisite to reconcile all the discordant results to clarify its role in cancer susceptibility." (PMID 26891331, 2016). "We analyzed DCC in more detail based on its known critical function as a netrin-1 dependence receptor and its implications in various cellular key functions including axon guidance, cell migration, and pro-apoptotic activities; the latter known to be impaired in numerous cancer types." (PMID 27096627, 2016). "Netrin receptor functions have been implicated in tumorigenic processes such as angiogenesis, apoptosis, and cell invasion, thus suggesting UNC-5 or UNC-40/DCC as targets for cancer therapy that might be less deleterious to normal cells than targeting small GTPases." (PMID 26292279, 2015). "We found that NTN1, DCC, DSCAM, MCAM, and UNC5D were methylated in many cancers, of which UNC5D was the most prominent." (PMID 41407823, 2025). "Among the four selected candidate genes, DCC, PTGDR1, EDNRB, and ECAD, the promoter regions of all genes except PTGDR1 showed significantly higher methylation values in cancer areas than in normal mucosa areas." (PMID 38538728, 2024). "Notably, Deciphera’s ULK1/2 inhibitor, DCC-3116, is in clinical trial with RAS/MAPK pathway mutation (ClinicalTrials.gov, NCT04892017, accessed on 20 December 2022), because treatment of RAS mutant cancer cells with MAPK pathway inhibitors increases autophagy for cancer cell survival." (PMID 36674464, 2023).